PIGX (phosphatidylinositol glycan anchor biosynthesis class X)
Description:
Stabilizing subunit of the glycosylphosphatidylinositol-mannosyltransferase I complex which catalyzes the transfer of the first mannose, via an alpha-1,4 bond from a dolichol-phosphate-mannose (Dol-P-Man) to the glucosaminyl acyl phosphatidylinositol (GlcN-(acyl)PI) intermediate to generate alpha-D-Man-(1->4)-alpha-D-GlcN-(1->6)-(1-radyl,2-acyl-sn-glycero-3-phospho)-2-acyl-inositol and participates in the sixth step of the glycosylphosphatidylinositol-anchor biosynthesis. Probably acts by stabilizing the mannosyltransferase PIGM.
Synonyms: PIG-X; FLJ20522
Tractability: Antibody: UniProt predicts a signal peptide or a membrane-spanning region; the Human Protein Atlas places it where antibodies can reach. PROTAC: ubiquitination databases record sites on it.
Gene: Protein-coding gene on chromosome 3 (196,639,775 to 196,736,007, forward strand). Ensembl gene ENSG00000163964.
Subcellular location: Endoplasmic reticulum membrane
Subcellular location (Human Protein Atlas): Cytosol; Nucleoplasm; Plasma membrane
Pathways (Reactome):
Metabolism of proteins: Synthesis of glycosylphosphatidylinositol (GPI)
Gene Ontology:
Biological process: GPI anchor biosynthetic process
Cellular component: endoplasmic reticulum membrane; glycosylphosphatidylinositol-mannosyltransferase I complex
Genetic constraint (gnomAD): Loss-of-function variants: 5 observed, 5.5 expected, observed/expected ratio (o/e) 0.91, 90% interval 0.47 to 1.74. That is too few expected variants to judge how well the gene tolerates losing a copy. Missense variants: 85 observed, 86.35 expected, observed/expected ratio (o/e) 0.98, 90% interval 0.82 to 1.18. Synonymous variants: 27 observed, 30.68 expected, observed/expected ratio (o/e) 0.88, 90% interval 0.65 to 1.21.
Homologues: Orthologues: chimpanzee PIGX (96% identical), macaque PIGX (89% identical), mouse Pigx (74% identical), rat Pigx (74% identical), dog PIGX (72% identical), pig PIGX (71% identical), guinea pig PIGX (68% identical), tropical clawed frog pigx (36% identical), zebrafish pigx (27% identical), Drosophila melanogaster PIG-X (16% identical).
Diseases named in the same sentence as PIGX in open-access papers:
PIGX is named in the same sentence as 7 diseases in open-access papers, as found by Europe PMC text mining. Sharing a sentence is not in itself a finding about the gene and the disease. The quoted sentences say what the papers report.
breast carcinoma (4 papers, 2018 to 2023). "The association of the PAK2_rs9325377*A with higher PIGX expression further reinforces this possibility, since PIGX knockdown may inhibit breast cancer cell growth." (PMID 31681304, 2019). "In breast cancer cells, RCN1 forms a complex with PIGX and RCN2 that negatively regulates the expression of ZIC family member 1 (ZIC1) and EH domain‐containing protein 2 (EHD2), promoting breast carcinogenesis." (PMID 37746742, 2023). "PIGX plays an important role in the biosynthetic pathway of glycosylphosphatidylinositol (GPI)-anchor motif and is found to be highly upregulated in breast cancer cells." (PMID 30984618, 2019).
gastric cancer (1 paper, 2021). A primary or metastatic malignant neoplasm involving the stomach. "In breast, bladder, and gastric cancer, the high expression of other GPI-anchor biosynthesis glycogenes, such as PIGU, PIGT, and PIGX, is associated with oncogenesis, poor prognosis, and tumorigenesis." (PMID 34540372, 2021).
cancer (3 papers, 2018 to 2022). A tumor composed of atypical neoplastic, often pleomorphic cells that invade other tissues. "GPAA1, PIGZ and PIGX amplifications are associated with worse prognosis at a pan-cancer level." (PMID 36009354, 2022).
PIGX also shares sentences with these, for which no sentence is quoted: infection (1 paper); sleeping sickness (1); tumor (1); visceral leishmaniasis (1).